LAMA2 (laminin subunit alpha 2)
Description:
Binding to cells via a high affinity receptor, laminin is thought to mediate the attachment, migration and organization of cells into tissues during embryonic development by interacting with other extracellular matrix components.
Synonyms: LAMM; MDC1A
Tractability: Antibody: its Gene Ontology location is reachable by antibodies, with high confidence; UniProt places it where antibodies can reach, with medium confidence; UniProt predicts a signal peptide or a membrane-spanning region. PROTAC: ubiquitination databases record sites on it. Other modalities: an approved drug acts on it.
Gene: Protein-coding gene on chromosome 6 (128,883,138 to 129,516,566, forward strand). Ensembl gene ENSG00000196569.
Subcellular location: Secreted, extracellular space, extracellular matrix, basement membrane
Pathways (Reactome):
Extracellular matrix organization: ECM proteoglycans; Formation of the dystrophin-glycoprotein complex (DGC); Laminin interactions; Non-integrin membrane-ECM interactions
Developmental Biology: Developmental Lineage of Pancreatic Ductal Cells; EGR2 and SOX10-mediated initiation of Schwann cell myelination
Disease: Attachment of bacteria to epithelial cells
Signal Transduction: MET activates PTK2 signaling
Gene Ontology:
Molecular function: extracellular matrix structural constituent; structural molecule activity; signaling receptor binding
Biological process: maintenance of blood-brain barrier; muscle organ development; nervous system development; positive regulation of cell adhesion; positive regulation of integrin-mediated signaling pathway; positive regulation of muscle cell differentiation; regulation of basement membrane organization; signal transduction; cell adhesion; regulation of cell adhesion; regulation of cell migration; regulation of embryonic development; Schwann cell differentiation
Cellular component: basement membrane; extracellular matrix; extracellular region; laminin-12 complex; laminin-2 complex; laminin-4 complex; plasma membrane; protein complex involved in cell-matrix adhesion; synapse; dendritic spine; neuromuscular junction; sarcolemma; synaptic cleft
Genetic constraint (gnomAD): Loss-of-function variants: 208 observed, 291.4 expected, observed/expected ratio (o/e) 0.71, 90% interval 0.64 to 0.8. The upper end of that interval is the gene's LOEUF score, 0.8, which puts it in group 3 of 6, group 1 being the genes least tolerant of losing a copy. Missense variants: 3,338 observed, 3,545.9 expected, observed/expected ratio (o/e) 0.94, 90% interval 0.91 to 0.97. Synonymous variants: 1,231 observed, 1,276.9 expected, observed/expected ratio (o/e) 0.96, 90% interval 0.92 to 1.01.
Gene-disease validity (ClinGen):
ClinGen rates the evidence that LAMA2 causes each of these diseases.
LAMA2-related muscular dystrophy (autosomal recessive): Definitive. Any muscular dystrophy in which the cause of the disease is a mutation in the LAMA2 gene.
Homologues: Orthologues: chimpanzee LAMA2 (99% identical), macaque LAMA2 (98% identical), rabbit LAMA2 (92% identical), dog LAMA2 (89% identical), mouse Lama2 (88% identical), rat Lama2 (88% identical), guinea pig LAMA2 (88% identical), tropical clawed frog lama2 (67% identical), zebrafish lama2 (16% identical). Paralogues in human: LAMA1 (45% identical), LAMA5 (25% identical), LAMA3 (24% identical), HSPG2 (18% identical), USH2A (15% identical), LAMB2 (13% identical), LAMA4 (13% identical), LAMB1 (13% identical), LAMC1 (13% identical), AGRN (12% identical), LAMB4 (12% identical), LAMC3 (12% identical), and 15 more.
Diseases named in the same sentence as LAMA2 in open-access papers:
LAMA2 is named in the same sentence as 178 diseases in open-access papers, as found by Europe PMC text mining. Sharing a sentence is not in itself a finding about the gene and the disease. The quoted sentences say what the papers report.
muscular dystrophy (89 papers, 2010 to 2026). Muscular dystrophy (MD) refers to a group of more than 30 genetic diseases characterized by progressive weakness and degeneration of the skeletal muscles that control movement. "Seven cases of milder form of LAMA2-associated muscular dystrophies (MDs) were confirmed in the current study." (PMID 39941024, 2025). "The proband’s clinical data (including brain MRI) corresponded to LAMA2-associated muscular dystrophy, and the detected variants were located in trans position (variant c.172T>C inherited from mother and variant ex40 del inherited from father)." (PMID 39941024, 2025). "In Russia, the approximate calculated prevalence of LAMA2-associated muscular dystrophies (MDs) is 1 in 117,700." (PMID 39941024, 2025). "Mutations in LAMA2 cause forms of muscular dystrophy due to weak interstitial connections between striated muscle cells." (PMID 41026613, 2025). "The estimated prevalence of LAMA2-associated muscular dystrophy in Russia is approximately 1 in 117,700." (PMID 39941024, 2025). "The patient’s clinical findings, including their brain MRI, were consistent with LAMA2-associated muscular dystrophy." (PMID 39941024, 2025). "Previous studies have reported cases with concurrent TTN and LAMA2 mutations, highlighting overlapping features of muscular dystrophy." (PMID 39926328, 2025). "We analyzed the clinical and molecular genetic data of Russian patients with LAMA2-associated muscular dystrophies (MDs)." (PMID 39941024, 2025). "In 83 of 90 cases, patients were diagnosed with the more severe form of LAMA2-associated muscular dystrophy." (PMID 39941024, 2025). "LAMA2-associated muscular dystrophy is a rare genetic disorder caused by pathogenic or likely pathogenic variants in the LAMA2 gene." (PMID 39941024, 2025). "Data were collected and analyzed from patients with confirmed diagnoses of LAMA2-associated muscular dystrophy using various molecular genetic methods in research centers from 2008 to 2024." (PMID 39941024, 2025). "The approximate calculated prevalence of LAMA2-associated muscular dystrophies (MDs) is 1 in 117,700." (PMID 39941024, 2025). "This study presents the spectrum of pathogenic or likely pathogenic variants in patients with LAMA2-associated muscular dystrophy residing in the Russian Federation and provides an assessment of its prevalence within the region." (PMID 39941024, 2025). "Among other muscular dystrophies, 20 of 24 patients (83.3%) had variants in LAMA2 (n = 6), LMNA (n = 5), COL6A1 (n = 4), CHKB (n = 2), COL6A2 (n = 2), and COL6A3 (n = 1)." (PMID 40494860, 2025). "It is worth noting that missense variants were found exclusively in patients with the milder form of LAMA2-associated muscular dystrophy." (PMID 39941024, 2025). "To assess the development of muscular dystrophy from early to late postnatal periods to better understand the pathogenic processes in human LAMA2-CMD, we observed the muscle pathology at different ages and stages." (PMID 40960171, 2025). "At the Research Centre for Medical Genetics (RCMG) and LLC “Genomed”, 90 unrelated patients with LAMA2-associated muscular dystrophy were identified." (PMID 39941024, 2025). "LAMA2-associated muscular dystrophy is a rare neuromuscular disorder with an autosomal recessive inheritance pattern caused by pathogenic or likely pathogenic variants in the LAMA2 gene." (PMID 39941024, 2025). "Mutations in the alpha-2 subunits of the laminin gene (LAMA2) cause an autosomal recessive congenital muscular dystrophy (CMD) subtype known as laminin a2-related muscular dystrophies (LAMA2-RD)." (PMID 38975466, 2024). "LAMA2-related muscular dystrophy (LAMA2 MD or MDC1A) is caused by mutations in LAMA2, the gene coding for the laminin-α2 chain of the heterotrimeric laminins, composed of α, β, and γ chains." (PMID 37038437, 2023).
muscular dystrophy (continued). "Four pathogenic/likely pathogenic LAMA2 variants have been reported in Vietnamese patients with muscular dystrophy, including c.778C>T (p.H260Y) and c.2987G>A (p.C996Y), c.1964T>C (p.L655P) and c.3556-13T>A." (PMID 37388928, 2023). "Representative of the spectrum of disease severity in humans, several mouse models of LAMA2-related muscular dystrophy have been generated that express varying levels of mutated LAMA2 gene products or are full knockouts." (PMID 36523505, 2022). "Loss of the laminin α2 chain in LAMA2-related muscular dystrophy patients and mutant mice leads to a compensatory upregulation of laminin α4, which binds only weakly to dystroglycan and integrin α7β1, and does not effectively autopolymerize." (PMID 36523505, 2022). "Dysfunctional laminin α2 caused by mutations within the LAMA2 gene encoding laminin α2 results in LAMA2-related muscular dystrophies (MDC1A), the most common subtype of congenital muscular dystrophy." (PMID 34982945, 2022). "Loss of LAMA2 causes Muscular Dystrophy, Congenital Merosin-Deficient, 1a (MDC1A; OMIM: 607855), while partial LAMA2 deficiency results in LGMDR23 (OMIM: 618138)." (PMID 34740639, 2022). "The clinical presentation of LAMA2-associated muscular dystrophies closely resembles that of the COLVI-related Bethlem myopathy, including muscle weakness, muscle hypotonia, and joint contractures." (PMID 34066978, 2021). "Lama2, while predominantly expressed in muscle tissue and implicated in diseases of muscular dystrophy has also recently been shown to inhibit osteogenesis and promote adipogenesis of mesenchymal stem cells (MSCs) via the hedgehog signaling pathway." (PMID 34394003, 2021). "Genetics consideration showed that mutation in LAMA2 caused a collection of muscle-wasting conditions called muscular dystrophy." (PMID 33558818, 2021). "LAMA2 MD and MDC1A are destructive muscular dystrophies caused by laminin α2 chain loss and have no cure." (PMID 32184725, 2020). "dy/dy mice have a spontaneous mutation in a non-coding region of the Lama2 gene that results in substantially reduced laminin-α2 levels, causing muscular dystrophy, nervous system involvement, and premature death." (PMID 32792907, 2020). "Mutations in LAMA2 result in the most common types of congenital muscular dystrophies, that is, LAMA2 MD or MDC1A (Congenital type 1A), which are characterized by disruption of laminin-211 and account for 10–30% of reported cases." (PMID 32184725, 2020). "The LAMA2 gene encodes the α2 subunit of laminins, and mutations in this gene have been shown to cause LAMA2-related muscular dystrophy." (PMID 32213190, 2020). "A less common entity is partial merosin deficiency, a disorder caused by partial loss of LAMA2 expression/function that is associated with a later onset, milder form of muscular dystrophy." (PMID 32742259, 2020). "The UK and Danish studies showed LAMA2 variants in about 2–3% of patients with mild muscular dystrophies or LGMD." (PMID 32848593, 2020). "Overall, WES enabled an accurate diagnosis of both patients with LAMA2-related muscular dystrophy and expanded the spectrum of missense variants in LAMA2." (PMID 32987775, 2020). "Partial laminin-211 deficiency can be caused not only by primarily LAMA2 mutations, but also secondarily by other muscular dystrophies, including dystroglycanopathy." (PMID 31133972, 2019). "This approach is illustrated by the development of two linker proteins to repair the LAMA2-deficient muscular dystrophy (LAMA2-MD)." (PMID 31920536, 2019). "Congenital muscular dystrophy with deficiency oflaminin α2 chain (LAMA2-CMD) is a very severe form of muscular dystrophy, for which notreatment is available." (PMID 30430039, 2018). "The patient was diagnosed postmortem as having early-onset LAMA2-related muscular dystrophy based on the results of mutations in LAMA2 (including a novel nonsense mutation: c.4452T>A/p.Cys1484X) identified by Sanger sequencing in his parents." (PMID 30147969, 2018).
muscular dystrophy (continued). "One of these genes is LAMA2, which is associated with muscular dystrophies and with the blood-brain barrier control." (PMID 28279172, 2017). "In mice, a complete loss of laminin-α2 results in severe muscular dystrophy and growth retardation while missense or splice-site mutations resulting in truncated Lama2 protein in muscle cause a less severe phenotype." (PMID 22952766, 2012). "Early pathology in mice with Lama2-deficient muscular dystrophy is marked by increased expression of TN-C in the extracellular matrix around muscle fibers, and decreased expression of LYVE-1 in lymphatic capillaries within the muscles." (PMID 21850221, 2011). "Apoptosis, ER stress and autophagy can each contribute to muscle pathogenesis in muscle diseases, including Lama2-deficient and other congenital muscular dystrophies." (PMID 21850221, 2011). "In one case (patient 49), the nucleotide sequence variant c.5562+5G>C was identified (in a compound heterozygous state with a deletion of exon 1), a variant reported by I. Naom in two patients with a milder clinical course of LAMA2-associated muscular dystrophy." (PMID 39941024, 2025). "The present study may serve as a foundation for further investigations of the various aspects of LAMA2-associated muscular dystrophies all over the world." (PMID 39941024, 2025). "Compared with other Lama2-deficient mice, including dy/dy, dy2J/dy2J, dy3k/dy3k, and dyW/dyW, the phenotype of the dyH/dyH mice was similar to that of the dy3k/dy3k mice, presenting with a very severe muscular dystrophy." (PMID 40960171, 2025). "In 7 out of 90 cases, a milder clinical form of LAMA2-associated muscular dystrophy was diagnosed." (PMID 39941024, 2025). "The proband’s clinical features, including brain MRI findings, were consistent with LAMA2-associated muscular dystrophy, and the identified variants were located in a trans position (variant c.7814del inherited from mother and variant c.2166A>T inherited from father)." (PMID 39941024, 2025). "LAMA2 mutations are also known to be associated with muscular dystrophy, while FBN1 mutations are linked to connective tissue abnormalities, including Marfan syndrome, which may also lead to scoliosis." (PMID 39926328, 2025). "The clinical features of the disease (including brain MRI findings) were also consistent with LAMA2-associated muscular dystrophy, and the variants were identified in a trans position (variant c.163A>C inherited from mother and variant ex40 del inherited from father)." (PMID 39941024, 2025). "However, null mutations of LAMA2 in humans manifest largely as a muscular dystrophy and there are only few patients that are reported to suffer from a peripheral neuropathy." (PMID 37038437, 2023). "In particular, mutations in the LAMA2 gene coding for the laminin α2 chain cause LAMA2-related muscular dystrophy, while mutations in the COL6A1, COL6A2, and COL6A3 genes lead to collagen VI-related myopathies, including Bethlem myopathy and Ullrich congenital muscular dystrophy." (PMID 36523505, 2022). "A recent study on a cohort of Chinese patients with LAMA2-related muscular dystrophy revealed an association of LGMDR23 with missense variants, leading to the hypothesis that missense pathogenic variants could be a predictor of a milder phenotype." (PMID 35928135, 2022). "In the group of congenital muscular dystrophies, 11 patients received a genetic diagnosis with mutations in the following genes: LAMA2 (three cases); POMGNT1 (one case); COL6 (one case); TTN (one case); GMPPB (one case); POMT2 (one case); POMGNT2 (one case); DMD (one case); and SCGA (one case)." (PMID 34675869, 2021). "Deficiency of LAMA2 is associated with muscular dystrophy and demyelinating neuropathy." (PMID 33995275, 2021). "Indeed, loss of function mutations of the LAMA2 gene in humans, and the Lama2 gene in rodents, results in muscular dystrophy, dysmyelinating neuropathy, and brain abnormalities." (PMID 32390798, 2020).
muscular dystrophy (continued). "In this study, we applied next-generation sequencing-based copy number variation profiling in 114 individuals clinically diagnosed with laminin α2-related muscular dystrophy, including 96 who harboured LAMA2 mutations and 34 who harboured intragenic rearrangements." (PMID 30301903, 2018). "LAMA2-related muscular dystrophy is due to defect in the gene encoding the α2 subunit, which together with β1 and γ1 chains form laminin-211 (Lm-211), the most prevalent laminin found in basement membrane (BM), surrounding muscle fibers, and also in the Schwann cells of peripheral nerves." (PMID 30147969, 2018). "Laminin-deficient congenital muscular dystrophy type 1A (LAMA2-CMD) is a severe form of muscular dystrophy caused by mutations in the LAMA2 gene encoding the laminin α2 chain that together with laminin β1 and γ1 chains form the heterotrimeric molecule laminin-211." (PMID 28771630, 2017). "To investigate the effects of the adhesion peptides in the context of an ECM-related pathology, we isolated myoblasts from dyW mice, a preclinical model of LAMA2-related muscular dystrophy." (PMID 41550718, 2026). "LAMA2, associated with congenital muscular dystrophy (alpha subunit-related) and LAMA2-related muscular dystrophy, was found in three patients." (PMID 40388540, 2025). "Data were obtained from 90 unrelated patients with LAMA2-associated muscular dystrophy, out of which 83 presented with the more severe form, MDC1A1, while seven had milder form of LAMA2-associated muscular dystrophy." (PMID 39941024, 2025). "In previous studies of LAMA2-MD, the focus on the pathogenesis of muscular dystrophy was primarily concentrated on the secondary histopathological changes such as fibrosis, inflammation, apoptosis, and metabolism." (PMID 40960171, 2025). "For example, in one patient initially suspected of having congenital muscular dystrophy, genetic analysis confirmed a LAMA2-related muscular dystrophy, offering a more specific etiological diagnosis." (PMID 40388540, 2025). "We show that mononuclear cells are also successfully transduced in the dyW/dyW mouse model of LAMA2-related muscular dystrophy." (PMID 40225019, 2025). "Inflammation plays a dual role in muscular dystrophies, including LAMA2-CMD and Duchenne muscular dystrophy (DMD)—initially facilitating muscle repair, but becoming detrimental when chronic, driving fibrosis and disease progression." (PMID 40161708, 2025). "Our understanding of the molecular pathogenesis of LAMA2-related muscular dystrophy (LAMA2-MD) requires improving." (PMID 40960171, 2025). "LAMA2-related muscular dystrophies (LAMA2-RDs) represent the most frequently reported subtype of CMDs, explaining away 30% of the cases." (PMID 38962616, 2024). "The association between the LAMA2 gene and arrhythmias has been explored in recent studies, showing that cardiac abnormalities and arrhythmias are present in a significant portion of cases with LAMA2-related muscular dystrophy." (PMID 38398418, 2024). "LAMA2-related muscular dystrophies (LAMA2-RDs) constitute the most prevalent subtype of congenital muscular dystrophies (CMDs)." (PMID 38962616, 2024). "In our previous study, the proportion of LGMD R23 phenotypes among all LAMA2-related muscular dystrophies was 10.8%." (PMID 37206914, 2023). "Two newborns were carriers of autosomal recessive LAMA2 muscular dystrophy (MD), two newborns were carriers of autosomal recessive limb‐girdle MD, and one newborn was a carrier of MD dystroglycanopathy." (PMID 37350320, 2023). "Both LAMA2 MD mice present with a severe hind limb paralysis but a much less severe muscular dystrophy than dyW/dyW or dy3K/dy3K mice." (PMID 37038437, 2023). "In one pregnancy, prenatal diagnosis was sought for two monogenic disorders, beta-thalassemia and LAMA2 related muscular dystrophy." (PMID 37301973, 2023).